MIR9-2 (microRNA 9-2)
Synonyms: hsa-mir-9-2; MIRN9-2; miRNA9-2; mir-9-2
Gene: MicroRNA gene on chromosome 5 (88,666,853 to 88,666,939, reverse strand). Ensembl gene ENSG00000284447.
Pathways (Reactome):
Cell-Cell communication: Regulation of CDH1 mRNA translation by microRNAs
Gene Ontology:
Biological process: miRNA-mediated post-transcriptional gene silencing
Cellular component: RISC complex
Homologues: Orthologues: chimpanzee ptr-mir-9-2 (100% identical), macaque mml-mir-9-2 (100% identical), dog MIR9-2 (99% identical), tropical clawed frog xtr-mir-9a-2 (91% identical), guinea pig MIR9-2 (83% identical), mouse Mir9-2 (83% identical), rabbit MIR9-2 (68% identical). Paralogues in human: MIR9-1 (84% identical), MIR9-3 (79% identical).
Diseases named in the same sentence as MIR9-2 in open-access papers:
MIR9-2 is named in the same sentence as 11 diseases in open-access papers, as found by Europe PMC text mining. Sharing a sentence is not in itself a finding about the gene and the disease. The quoted sentences say what the papers report.
Alzheimer disease (1 paper, 2021). A progressive, neurodegenerative disease characterized by loss of function and death of nerve cells in several areas of the brain leading to loss of cognitive function such as memory and language. "Although MIR9-2 has not been related to periodontal disease or other oral diseases in the literature, a close association has been reported between this gene and Alzheimer’s disease, whose prevalence is especially high among individuals with DS." (PMID 34200970, 2021).
attention deficit and hyperactivity disorder (1 paper, 2019). "In humans, MIR9-2, or its transcript expression, was already associated with schizophrenia, attention deficit and hyperactivity disorder (ADHD), and neuroticism, and a pleiotropic effect across disorders has been reported." (PMID 31434288, 2019).
internalizing disorder (1 paper, 2019). A type of mental or behavioral disorder, typically in children and young adults, with symptoms including depression, anxiety and withdrawal. "Our results suggest that rs4916723, close to the MIR9-2, has an important effect in the development of mental disorders, and more specifically in internalizing disorders." (PMID 31434288, 2019).
tumour (3 papers, 2017 to 2024). "Low expression of MIR9-2 was associated with tumour progression and MIR9-2-5p was found to play a role in the control of tumour stemness." (PMID 38693576, 2024). "Importantly, we have evidence that reduced MIR9-2 expression is associated with tumour progression and that the regulation of NANOG and MIR9-2 could be instrumental for developing therapies for the targeted treatment of TGCTs." (PMID 38693576, 2024). "Through gain-of-function experiments, MIR9-2 was further investigated as a novel tumour suppressor regulated by NANOG." (PMID 38693576, 2024). "Among these miRNAs, MIR9-2 was identified as a novel tumour suppressor involved in the regulation of TGCT stemness." (PMID 38693576, 2024). "The MIR9-2 promoter was methylated in 5 out of 10 NBTs and 58 out of 101 tumours (p = 0.744) and MIR9-3 promoter in 4 out of 10 NBT and in 71 out of 101 tumours (p = 0.075)." (PMID 28345661, 2017). "In this study, we showed that the expression of MIR9-2 is lower in EC and SEM than in normal testes and that its expression is lower in tumours expressing high levels of NANOG." (PMID 38693576, 2024). "We identified MIR182, MIR183, MIR371, MIR373, MIR512-1, MIR512-2, MIR515-1, and MIR520e exhibiting high expression and MIR216b, MIR887, MIR9-2, and MIR9-3 exhibiting low expression in NANOG H/L tumours." (PMID 38693576, 2024). "By contrast, MIR9-2 and MIR373 were methylated in both cancer cells and their normal counterparts, hence tissue-specific but not tumor-specific, pathologically irrelevant." (PMID 33076962, 2020).
cancer (2 papers, 2020 to 2024). A tumor composed of atypical neoplastic, often pleomorphic cells that invade other tissues. "We next assessed the effect of MIR9-2 expression on cell proliferation, invasion, and sensitivity to chemotherapy, which are hallmarks of cancer stemness." (PMID 38693576, 2024).
psychiatric disorder (2 papers, 2019 to 2021). A disorder characterized by behavioral and/or psychological abnormalities, often accompanied by physical symptoms. "This study aims to explore the role of polymorphisms of the genes MIR9-2 (rs4916723) and MIR34B/C (rs4938723) on the susceptibility of psychiatric disorders among children belonging to the 2004 Pelotas Birth Cohort study." (PMID 31434288, 2019). "This study aims to explore the role of genetic polymorphisms in the MIR9-2 (rs4916723) and MIR34B/C (rs4938723) genes on the susceptibility of psychiatric disorders in children from the 2004 Pelotas Birth Cohort." (PMID 31434288, 2019).
MIR9-2 also shares sentences with these, for which no sentence is quoted: mental disorder (1 paper); Obesity (1); oral diseases (1); periodontal disease (1); testicular germ cell tumour (1).